LINC00339 (long independently transcribed non-coding RNA 339)
Synonyms: HSPC157; NCRNA00339
Gene: Long non-coding RNA gene on chromosome 1 (22,024,558 to 22,031,223, forward strand). Ensembl gene ENSG00000218510.
Diseases named in the same sentence as LINC00339 in open-access papers:
LINC00339 is named in the same sentence as 14 diseases in open-access papers, as found by Europe PMC text mining. Sharing a sentence is not in itself a finding about the gene and the disease. The quoted sentences say what the papers report.
endometriosis (9 papers, 2017 to 2023). The growth of functional endometrial tissue in anatomic sites outside the uterine body. "Through an eQTL analysis of candidate genes and genetic variants in different tissues, an endometriosis risk-SNV rs3820282 is found to down-regulate LINC00339 expression by affecting the activity of LINC00339 promoter." (PMID 32523949, 2020). "Two cis-eQTLs overlap genomic regions associated with endometriosis with good evidence for the causal SNP in each region influencing endometriosis risk and the expression of LINC00339 on chromosome 1 or expression of VEZT on chromosome 12." (PMID 30061686, 2018). "Functional studies investigating the interaction between genetic variants on chr1p36.12 and nearby genes suggested that endometriosis risk variants interact with the promoters of LINC00339, CDC42 and WNT4 and the risk allele is associated with increased expression of CDC42 in blood cells." (PMID 36746607, 2023). "Two eQTLs were located in known risk regions for endometriosis including LINC00339 on chromosome 1 and VEZT on chromosome 12 and there was evidence for eQTLs that may be target genes in genomic regions associated with other reproductive diseases." (PMID 30061686, 2018). "Signals for mQTLs significantly associated with endometriosis on chromosome 1p36.12, including two potentially endometrial-specific mQTLs, were located in regulatory regions and associated with the expression of known genes of interest LINC00339, CDC42, and WNT410,24,41,42." (PMID 37587191, 2023). "Expression of several of these genes (LINC00339, CDC42, GDAP1, FGD6, SRP14) has been associated with risk of endometriosis previously." (PMID 37587191, 2023). "Such approaches identified that variants regulating the expression of genes involved in cell adhesion and proliferation, LINC00339, VEZT, FGD6, and CDC42, in endometrium and blood, also increase risk of endometriosis." (PMID 36746607, 2023). "Consistent with the importance of Wnt regulation, LINC00339 and its linked gene CDC42 are involved in both endometriosis and bone metabolism, two Wnt-regulated biological processes." (PMID 33092630, 2020). "Previous studies showed that linc00339 was involved in the development of endometriosis and progression of cancers." (PMID 31781497, 2019).
glioma (4 papers, 2020 to 2022). A benign or malignant brain and spinal cord tumor that arises from glial cells (astrocytes, oligodendrocytes, ependymal cells). "In conclusion, LINC00339 regulates VM formation by regulating the miR-539-5p/Twist1/MMP-2/MMP-14 pathway in glioma." (PMID 32169087, 2020). "LINC00339 also promoted glioma vasculogenic mimicry formation via regulating the miR-539-5p/TWIST1/MMPs axis." (PMID 32793467, 2020). "The forest plot shows that EPB41L4A.AS1, GDNF.AS1, HAR1A, LINC00237, SLC25A21.AS1, SNA13.AS1, and WDFY3.AS2 are the protective factors with HR < 1, while LINC00092, LINC00265, LINC00339, LINC00665, PAXIP1.AS2, SNHG16, SNHG9 and SOCS2.AS1 are risk factors with HR>1 in glioma patients." (PMID 35273128, 2022). "Results show the mean expression levels of LINC00665, LINC00339, SNHG16, PAXIPI.AS2 and LINC00092 in the glioma tissues are higher than those in the NBTs." (PMID 35273128, 2022). "Linc00339 inhibits the negative regulation of miR-539-5p on TWIST1 by competitively binding with miR-539-5p, enhances the ability of VM formation in glioma cells." (PMID 33542193, 2021).
breast carcinoma (2 papers, 2019 to 2020). "In breast cancer, miR-4656 acted downstream of linc00339 and was involved in cancer cell proliferation." (PMID 32536820, 2020). "To validate the mechanism underlying the effect of Huaier, we first examined the levels of linc00339 in Huaier treated breast cancer cell lines." (PMID 31781497, 2019). "After overexpression of linc00339, the tumor weights of breast cancer xenografts were increased." (PMID 31781497, 2019). "According to our study, linc00339 was increased in breast cancer cell lines compared with the normal epithelial cell, and linc00339 could promote triple-negative breast cancer progression through regulating miR-377-3p." (PMID 31781497, 2019). "Inhibition of linc00339 promoted the chemosensitivity of breast cancer cells to Huaier." (PMID 31781497, 2019). "Linc00339 could improve the chemoresistance of breast cancer to Huaier in vivo." (PMID 31781497, 2019). "Finally, we identified that Huaier could inhibit the proliferation of breast cancer cells through modulating linc00339/miR-4656/CSNK2B signaling pathway." (PMID 31781497, 2019). "Finally, linc00339/miR-4656/CSNK2B signaling pathway was identified and proved to mediate the inhibitory function of Huaier on breast cancer cells." (PMID 31781497, 2019).
gastric cancer (1 paper, 2020). A primary or metastatic malignant neoplasm involving the stomach. "LINC00339 could promote gastric cancer progression by increasing DCP1A expression level via inhibiting miR-377-3p." (PMID 32793467, 2020).
kidney stones (1 paper, 2021). "The LINC00339/miR‐22‐3p/NLRP3 axis in kidney stones induced by calcium oxalate promotes renal tubular epithelial pyroptosis." (PMID 33270361, 2021).
myopia (1 paper, 2019). "CDC42, a GTPase directly downstream of LINC00339, contained three significant variants in the two-point analysis, but has not previously been implicated in myopia either." (PMID 30704416, 2019).
nephritis (1 paper, 2015). Inflammation of renal tissue. "This more liberal view revealed FOS and LINC00339 (induction linked to nephritis), as well as MZB1 and TXNDC5 (induced in Type B patient samples), as increased in patients under steroid treatment." (PMID 26544975, 2015). "Other increased mRNAs linked to the presence of nephritis were C1orf86/FAAP20, coding for a DNA repair factor, and LINC00339, an uncharacterized noncoding RNA." (PMID 26544975, 2015).
cancer (4 papers, 2019 to 2025). A tumor composed of atypical neoplastic, often pleomorphic cells that invade other tissues. "LINC00339 has a known role in promoting the proliferation of several cancers, while there is also evidence to link CDC42 expression with CC invasion and migration." (PMID 36929174, 2023). "Linc00339 was then found to play a critical role in Huaier-mediated cancer suppression." (PMID 31781497, 2019). "Finally, in vitro and in vivo experiments confirmed that linc00339/miR-4656/CSNK2B signaling pathway played a critical role in the anti-cancer effects of Huaier extract." (PMID 31781497, 2019). "Our results support LINC00339 and CDC42/CDC42-AS1 as the most likely candidate genes in this locus, which is in line with evidence from other cancers." (PMID 36929174, 2023).
LINC00339 also shares sentences with these, for which no sentence is quoted: ovarian cancer (3 papers); cervical cancer (1); pancreatic carcinoma (1); reproductive diseases (1); triple-negative breast carcinoma (1); tumor (1).